PLCD1 (phospholipase C delta 1)
Description:
The production of the second messenger molecules diacylglycerol (DAG) and inositol 1,4,5-trisphosphate (IP3) is mediated by activated phosphatidylinositol-specific phospholipase C enzymes. Essential for trophoblast and placental development (By similarity). Binds phosphatidylinositol 4,5-bisphosphate.
Synonyms: PLC-III; NDNC3
Tractability: Antibody: its Gene Ontology location is reachable by antibodies, with high confidence. PROTAC: ubiquitination databases record sites on it; its protein half-life has been measured; a small molecule that binds it is known.
Target class: Enzyme; Hydrolase
Gene: Protein-coding gene on chromosome 3 (38,007,496 to 38,029,675, reverse strand). Ensembl gene ENSG00000187091.
Subcellular location: Cell membrane; Cytoplasm
Subcellular location (Human Protein Atlas): Microtubules
Pathways (Reactome):
Metabolism: Synthesis of IP3 and IP4 in the cytosol
Gene Ontology:
Molecular function: GTPase activating protein binding; phosphatidylinositol phospholipase C activity; phosphatidylinositol-4,5-bisphosphate binding; phosphatidylinositol-4,5-bisphosphate phospholipase C activity; protein binding; anion binding; calcium ion binding; phosphatidylinositol phosphate binding; phospholipase C activity; phosphoric diester hydrolase activity
Biological process: phosphatidylinositol metabolic process; phospholipase C-activating G protein-coupled receptor signaling pathway; phospholipase C/protein kinase C signal transduction; phospholipid metabolic process; intracellular signal transduction; lipid metabolic process; signal transduction
Cellular component: cytoplasm; cytoplasmic side of plasma membrane; extracellular exosome; plasma membrane; cytosol
Genetic constraint (gnomAD): Loss-of-function variants: 72 observed, 91.81 expected, observed/expected ratio (o/e) 0.78, 90% interval 0.65 to 0.95. The upper end of that interval is the gene's LOEUF score, 0.95, which puts it in group 4 of 6, group 1 being the genes least tolerant of losing a copy. Missense variants: 867 observed, 1,041 expected, observed/expected ratio (o/e) 0.83, 90% interval 0.79 to 0.88. Synonymous variants: 348 observed, 415.06 expected, observed/expected ratio (o/e) 0.84, 90% interval 0.77 to 0.92.
Homologues: Orthologues: chimpanzee PLCD1 (98% identical), macaque PLCD1 (98% identical), dog PLCD1 (93% identical), pig PLCD1 (92% identical), guinea pig PLCD1 (91% identical), rat Plcd1 (90% identical), mouse Plcd1 (90% identical), tropical clawed frog plcd1 (64% identical), zebrafish plcd1a (55% identical), zebrafish plcd1b (54% identical), Caenorhabditis elegans plc-3 (34% identical), Caenorhabditis elegans plc-4 (34% identical), and 3 more. Paralogues in human: PLCD3 (50% identical), PLCD4 (47% identical), PLCH2 (40% identical), PLCH1 (38% identical), PLCL1 (38% identical), PLCL2 (38% identical), PLCZ1 (33% identical), PLCG1 (33% identical), PLCG2 (33% identical), PLCB4 (33% identical), PLCB3 (32% identical), PLCE1 (32% identical), and 2 more.
Diseases named in the same sentence as PLCD1 in open-access papers:
PLCD1 is named in the same sentence as 54 diseases in open-access papers, as found by Europe PMC text mining. Sharing a sentence is not in itself a finding about the gene and the disease. The quoted sentences say what the papers report.
breast carcinoma (15 papers, 2011 to 2024). "In this study, we found that PLCD1 was downregulated in breast cancers, and the gain-or-loss functional assay revealed that PLCD1 inhibited cell migration and invasion in vitro via the ERK1/2/β-catenin/MMP7 signalling pathway." (PMID 28423710, 2017). "It is interesting that MMP7 protein levels were inhibited by PLCD1 in gastric and breast cancer in our previous work, even though the underlying mechanism is not known." (PMID 28423710, 2017). "Consistently, our observation of associations between PLCD1 and breast cancer further proved its carcinogenic potential." (PMID 25683757, 2015). "PLCδ1 expression is downregulated in various diseases, such as breast cancer and esophageal squamous cell carcinoma, indicating that PLCδ plays an inhibitory role in tumor pathology." (PMID 37370855, 2023). "Previously, our laboratory identified the tumor inhibitory function of PLCD1 in breast cancer by inducing cell cycle G2/M arrest." (PMID 36849889, 2023). "PLCD1 was previously disclosed to inhibit diseases, airway smooth muscle hypertrophy, colorectal cancer, and breast cancer contained." (PMID 37228901, 2023). "PLCδ1 acts as a tumor-suppressor gene in various tumors, and it is epigenetically silenced through hypermethylation in esophageal squamous cell carcinoma, breast cancer, gastric cancer, and chronic myeloid leukemia." (PMID 37370855, 2023). "Expression of PLCD1 is downregulated in breast cancer cell lines and primary breast cancers following aberrant hypermethylation of its promoter." (PMID 28423710, 2017). "PLCD1 inhibits MMP7 expression, resulting in anti-tumour effects in gastric and breast cancers, but the underlying mechanism remains elusive." (PMID 28423710, 2017). "In this study, expression of PLCD1 was also detected in a panel breast cancer cell lines and three normal breast tissues by RT-PCR." (PMID 28423710, 2017). "Taken together, these results indicate that PLCD1 functions as a tumour suppressor affecting cell migration and invasion in breast cancer." (PMID 28423710, 2017). "This region includes the candidate tumour suppressor PLCD1, the promoter of which is frequently aberrantly hypermethylated in breast cancers." (PMID 28423710, 2017). "It is located at 3p22 in a region that is frequently deleted in multiple cancers, and the PLCD1 enzyme is a potential tumour suppressor in breast cancer that inhibits matrix metalloprotease (MMP) 7, but the detailed mechanism remains elusive." (PMID 28423710, 2017). "Similar to the high level of expression of cytosolic Gαh, increased protein levels of PLCδ1 was identified as poor prognostic factor in patients with breast cancer." (PMID 28576130, 2017). "The strongest gene-based association was PLCD1 for pancreatic cancer and prostate cancer, PIK3C2B for breast cancer, and INPP5K for bladder cancer, respectively." (PMID 25683757, 2015). "PLCD1 has been confirmed to play a cancer suppressive effect in colorectal cancer, gastric cancer, esophageal squamous carcinoma, pancreatic cancer, breast cancer, chronic myeloid leukemia." (PMID 37460940, 2023). "For instance, PLCD1 inhibits tumor formation in breast cancer by inducing apoptosis." (PMID 33428603, 2021). "Recent studies have reported PLCδ1 as a tumor suppressor in breast cancer and ESCC." (PMID 32276377, 2020). "Methylation of PLCD1 can be regulated to improve the treatment of breast cancer." (PMID 32170852, 2020). "Consistent with this viewpoint, in the present study, PLCD1 was downregulated in breast cancers." (PMID 28423710, 2017). "Moreover, in breast cancer, we demonstrated that PLCD1 inhibits cell proliferation and cell migration." (PMID 28423710, 2017). "Cell migration is suppressed in breast cancer cells expressing PLCD1." (PMID 28423710, 2017). "Moreover, the signature of the combination of high cytosolic Gαh and high PLCδ1 appeared to significantly predict a worse outcome in breast cancer patients." (PMID 28576130, 2017).
breast carcinoma (continued). "In addition, the Cox multivariate analysis of disease-free survival indicated that increased PLCδ1 level and the signature of high cytosolic Gαh/PLCδ1 were independent predictive factors of poor outcomes in breast cancer patients." (PMID 28576130, 2017). "Moreover, histological analysis revealed that the formation of tumor colonies in the lungs was clearly suppressed in the orthotropic mouse model of breast cancer after the treatment with Myr-PLCδ1 peptide compared to that with the control peptide for 3 weeks." (PMID 28576130, 2017). "Moreover, clinicopathological analyses revealed that the combined signature of high Gαh/PLCδ1 levels indicates worse prognosis in patients with breast cancer and correlates with lymph node metastasis of ER-negative breast cancer." (PMID 28576130, 2017). "PLCD1 has also been identified as a TSG in gastric cancer, oesophageal squamous cell carcinoma, KRAS-mutated colorectal cancer, chronic myeloid leukaemia, and breast cancer in our previous work." (PMID 28423710, 2017). "In the present study, expression of PLCD1 in primary breast cancers was investigated." (PMID 28423710, 2017). "Also, PLCD1 suppresses cell migration and invasion in breast cancers." (PMID 28423710, 2017). "PLCD1 has been demonstrated to suppress MMP7 levels and thereby regulate cell migration in high-stage gastric and breast cancers." (PMID 28423710, 2017). "Collectively, our findings suggest that PLCD1 acts as a tumour suppressor, by KIF3A-mediated suppression of ERK1/2/β-catenin/MMP7 signalling, at least in part, in breast cancer." (PMID 28423710, 2017). "Therefore, KIF3A was demonstrated to mediate the effect of PLCD1 on ERK1/2/β-catenin/MMP7 signalling, at least in part, in breast cancer." (PMID 28423710, 2017). "In this study, expression of PLCD1 was detected in a panel of breast cancer tissues that were matched with non-cancerous adjacent breast tissue samples, but PLCD1 was markedly downregulated in breast cancer tissue." (PMID 28423710, 2017). "In the present study, PLCD1 suppressed phosphorylation of ERK but did not affect Akt phosphorylation in breast cancer (data not shown)." (PMID 28423710, 2017). "However, this has so far only been confirmed in PLCD1 within a range of 52–62% methylation in ESCC, gastric and breast cancer." (PMID 21909432, 2011). "Silence of PLCD1 by promoter CpG methylation has been described in a few epithelial and hematological malignancies, including gastric cancer (GsCa), ESCC, colorectal cancer (CRC), breast cancer (BrCa), pancreatic cancer (PAAD), chronic myeloid leukemia (CML) and non-small cell lung cancer (NSCLC)." (PMID 36849889, 2023). "Thus, the suppressive effect of PLCD1 may depend on crosstalk between β-catenin signalling and ERK signalling in breast cancer." (PMID 28423710, 2017). "In this study, there was a negative correlation between the expression of PLCD1 and KIF3A in breast cancer." (PMID 28423710, 2017).
colorectal cancer (7 papers, 2008 to 2023). A primary or metastatic malignant neoplasm that affects the colon or rectum. "Furthermore, PLCD1 inhibits the epithelial-mesenchymal transition (EMT) of KRAS-mutated colorectal cancers." (PMID 28423710, 2017). "It has been reported that E-cadherin engagement leads to ERK inhibition in a PI3K/Akt-dependent pathway in differentiating intestinal epithelial cells, and in KRAS-mutated colorectal cancers, suggesting PLCD1 may suppress phosphorylation of ERK by engaging E-cadherin." (PMID 28423710, 2017). "Previous research shows the PLCD1 expression is downregulated in colorectal cancer cells, leading to induce E-cadherin expression, and PLCD1 overexpression reduced the malignant progression via E-cadherin and KRAS/MEK/ERK signal attenuation." (PMID 35836489, 2022). "The two genes, which were analysed in both studies, DLEC1 and its neighbour PLCD1, are silenced through DNA methylation and H3-K9 dimethylation in colorectal cancer whereas in bladder cancer they are silenced through histone H3-K9 trimethylation." (PMID 18594535, 2008). "Indeed, PLCD1 induces cell cycle arrest by inhibiting Akt signalling in ESCC, and suppresses EMT through ERK signalling in KRAS-mutated colorectal cancers." (PMID 28423710, 2017).
gastric cancer (5 papers, 2013 to 2023). A primary or metastatic malignant neoplasm involving the stomach. "On the other hand, PLCδ1 expression is downregulated in about 84% of gastric cancer cell lines and this correlates with PLCδ1 promoter methylation." (PMID 32276377, 2020). "Ectopic expression of PLCδ1 in PLCδ1 downregulated gastric cancer cells significantly inhibits cell migration." (PMID 32276377, 2020). "In high-stage gastric cancers, PLCD1 regulates cell proliferation, and migration and metastasis in vivo." (PMID 28423710, 2017).
pancreatic cancer (5 papers, 2015 to 2023). "In pancreatic cancer, rs11922130 and rs9861030 across gene PLCD1 and rs11044171 across PIK3C2G were associated with cancer risk (P < 0.001)." (PMID 25683757, 2015). "First, the sample size used for the survival analysis was not large enough, which led to many false‐negative results regarding PLCD1 and PLCD4, especially since PLCD1 has been shown to inhibit pancreatic cancer cell growth in other studies." (PMID 31808619, 2020). "Phospholipase C δ1 (PLCD1) manipulates the biological behaviors of pancreatic cancer cells." (PMID 32170852, 2020).
chronic myeloid leukemia (4 papers, 2020 to 2023). "Epigenetic inactivation of PLCD1 occurs in chronic myeloid leukemia." (PMID 32170852, 2020).
esophageal squamous cell carcinoma (4 papers, 2017 to 2024). Esophageal squamous cell carcinoma (ESCC) is a type of esophageal carcinoma (EC) that can affect any part of the esophagus, but is usually located in the upper or middle third. "In oesophageal squamous cell carcinoma (ESCC), PLCD1 was first reported as a tumour suppressor following single nucleotide polymorphism-mass array experiments in which PLCD1 suppressed cell cycle progression and cell migration." (PMID 28423710, 2017). "For instance, PLCD1 suppresses the proliferation, invasion, and migration of esophageal squamous cell carcinoma by suppressing the Wnt/β-catenin signaling pathway." (PMID 36171236, 2022).
Pilar cyst (4 papers, 2020 to 2026). "In summary, we have used WES to identify a mutation in PLCD1 (p.S745L) that is present in 100% of familial trichilemmal cysts." (PMID 32265483, 2020). "Our results indicate that familial trichilemmal cysts result from a combination of germline and somatic mutations on the same copy of the PLCD1 gene." (PMID 32265483, 2020). "Congenital pilar cysts are associated with mutations in the phospholipase C delta one gene (PLCD1)." (PMID 35547435, 2022). "Given that our cohort with familial trichilemmal cysts all harbored germline variants or mutations in exon 9 and somatic mutations in exon 15 of PLCD1, we asked whether apparently sporadic trichilemmal cysts were a distinct genetic entity or merely the result of incomplete penetrance." (PMID 32265483, 2020).
triple-negative breast carcinoma (3 papers, 2017 to 2024). An invasive breast carcinoma which is negative for expression of estrogen receptor (ER), progesterone receptor (PR), and human epidermal growth factor receptor 2 (HER2). "The interaction of transglutaminase 2 and phospholipase C δ1 (PLCδ1) promotes Akt/mTORC1 activation and, consequently, autophagosome degradation in metastatic triple-negative breast cancer." (PMID 39329960, 2024).
abdominal aortic aneurysm (2 papers, 2023 to 2025). Enlargement and ballooning of the vessel that supplies arterial blood to the abdomen, pelvis and legs. "In vascular smooth muscle cells, miR-191-5p targets PLCD1 to regulate apoptosis and inflammation, contributing to the progression of abdominal aortic aneurysms." (PMID 40504789, 2025).
alopecia (2 papers, 2012 to 2023). Hair loss usually from the scalp. "It has previously been suggested that the alopecia of mice with functional inactivation of Plcd1 develops in the context of an inflammatory response." (PMID 22723964, 2012). "Inactivation of Plcd1 alone causes loss of hair (alopecia), whereas inactivation of Plcd3 alone has no apparent phenotypic effect." (PMID 22723964, 2012). "Mice with nonfunctional PLCD1, normally a negative regulator of proinflammatory cytokine production in macrophages, display alopecia and an inflammatory phenotype in the skin." (PMID 37000833, 2023).
cardiomyopathy (2 papers, 2014 to 2015). A disease of the heart muscle or myocardium proper. "In this study, we demonstrated that the simultaneous loss of PLCδ1 and PLCδ3 induces cardiac fibrosis, hypertrophy of cardiomyocytes, so-called pathological remodeling, and cardiomyopathy." (PMID 24810051, 2014). "Several studies reported that DOX induced the loss of phospholipase C delta-1 (PLCD-1) and PLCD-3 that simultaneously led to cardiomyocyte apoptosis and the development of cardiomyopathy." (PMID 26491536, 2015).
colon carcinoma (2 papers, 2011 to 2023). "Complete or partial methylation of the PLCD1 promoter was found in 79% (15/19) of the colon cancer cell lines, detected by qualitative as well as quantitative methylation-specific polymerase chain reaction (MSP and qMSP, respectively)." (PMID 21909432, 2011). "In colon cancer, the downregulation of PLCδ1 leads to a reduction in cellular apoptosis and an increase in cellular proliferation, invasion, and migration; therefore, PLCδ1 is described as a potential biomarker of colon cancer." (PMID 37370855, 2023). "The repression of PLCD1 is in accordance with the results presented by Nomoto and colleagues in 1995, where they report undetectable levels of PLCD1 protein in eight colon cancer cell lines and decreased levels in twelve of thirteen colon carcinomas compared with their paired normal mucosa sample." (PMID 21909432, 2011). "Our results from qMSP and bisulfite sequencing cannot confirm PLCE1 as a target for this type of epigenetic silencing, and despite high frequency of methylation in colon cancer cell lines, methylation in the PLCD1 promoter can only explain reduced expression in a subgroup of the carcinomas." (PMID 21909432, 2011).
cyst (2 papers, 2020 to 2022). A sac-like closed membranous structure that may be empty or contain fluid or amorphous material. "Mouse studies suggest the loss of PLCD1 function can promote trichilemmal cyst formation." (PMID 32265483, 2020).
esophageal cancer (2 papers, 2023 to 2025). A primary or metastatic malignant neoplasm involving the esophagus. "Upregulation of PLCD1 can inhibit the activity of β-catenin pathway in esophageal cancer." (PMID 37460940, 2023).
heart failure (2 papers, 2011 to 2014). Inability of the heart to pump blood at an adequate rate to meet tissue metabolic requirements. "The findings of this study suggest that PLCδ1 and PLCδ3 are possible therapeutic targets for DCM and cardiac remodeling that leads to heart failure." (PMID 24810051, 2014). "Future work will determine whether the expression and/or activity of PLCδ1 and PLCδ3 in patients with DCM and/or heart failure are decreased." (PMID 24810051, 2014).
nail disorder (2 papers, 2019 to 2022). A disease involving the nail. "Pathogenic variants of five genes (RSPO4, FZD6, HPGD, PLCD1, and COL7A1) have been reported to cause congenital pure nail disorders, among which FZD6 (frizzled class receptor 6) and RSPO4 are responsible for most of the cases." (PMID 36421794, 2022). "The genes associated with human hereditary nail disorders are listed as HPGD, RSPO4, PLCD1, COL7A1 and FZD6." (PMID 30642273, 2019).
bipolar disorder (1 paper, 2015). A disorder of the brain that causes unusual shifts in mood, energy, activity levels and the ability to carry out day-to-day tasks. "The association between PLCD1 and IMPA2 in Group 1 in each age interval also is of interest because IMPA2, which dephosphorylates myo-inositol monophosphate within the “PI cycle”, has been proposed as the preferred target of lithium in the treatment bipolar disorder." (PMID 26168237, 2015).
breast tumor (1 paper, 2024). "Tumor tissues treated with PLCD1 showed a more orderly spatial organization of breast tumor cells, as validated by hematoxylin and eosin staining." (PMID 38967113, 2024).